CCN3 (cellular communication network factor 3)
Diseases named in the same sentence as CCN3 in open-access papers (continued):
Sharing a sentence is not in itself a finding about the gene and the disease.
Cirrhosis (2 papers, 2019 to 2023). A chronic disorder of the liver in which liver tissue becomes scarred and is partially replaced by regenerative nodules and fibrotic tissue resulting in loss of liver function. "Moreover, increased CCN3 is associated with metastasis, more severe cirrhosis, increased EMT, and further inversely related to the prognosis of HCC." (PMID 37166689, 2023). "High expression of CCN3 was localized to hepatic cells and associated with more severe cirrhosis." (PMID 31029128, 2019). "CCN3 expression was higher in patients with cirrhosis (26.47 ± 9.81 vs. 18.73 ± 14.27 p = 0.0189), supporting a correlation between CCN3 levels in liver tissues and cirrhosis." (PMID 31029128, 2019). "Relatively low levels of CCN3 were detected in HCC patients who had moderate to mild cirrhosis compared with those who had severe cirrhosis, although this difference was not statistically significant." (PMID 31029128, 2019). "We further showed that CCN3 was inversely related to cirrhosis in the prognosis of HCC and inhibited expression of α-SMA and TGF-β1 in HSCs." (PMID 31029128, 2019). "To better understand the relationship between CCN3 and cirrhosis in the prognosis of HCC, we classified patients into two groups based on CCN3 expression level." (PMID 31029128, 2019). "Tissue microarrays also demonstrated that increased expression of CCN3 in hepatic cells correlated with the level of cirrhosis." (PMID 31029128, 2019). "Although cirrhosis promoting tumors progression is very clearly, while cirrhosis was insufficient factor alone to predict prognosis of patients with HCC, cause of many cytokines such as CCN3 may influence the relationship between cirrhosis and HCC progression." (PMID 31029128, 2019). "Finally, CCN3 was inversely related to cirrhosis in the prognosis of HCC and negatively regulated hepatic stellate cells (HSCs) in vitro with downregulation of α-SMA, TGF-β, and collagens." (PMID 31029128, 2019). "Patients with cirrhosis were further divided into two subgroups according to CCN3 expression." (PMID 31029128, 2019). "Therefore, CCN3 paracrine effects from hepatic cells may be closely related to cirrhosis and may play an important role in HCC progression." (PMID 31029128, 2019). "Finally, correlations between CCN3 and cirrhosis were explored in patients." (PMID 31029128, 2019). "Patients with high expression of CCN3 were further divided into two subgroups according to the presence or absence of cirrhosis." (PMID 31029128, 2019). "CCN3 expression was significantly higher in HCC patients with moderate cirrhosis compared with those who had no cirrhosis (0.010 ± 0.021 vs. 0.0019 ± 0.0026 p = 0.018)." (PMID 31029128, 2019). "In patients with low CCN3 expression, patients with cirrhosis had significantly worse prognosis than patients without cirrhosis." (PMID 31029128, 2019). "CCN3 expression was significantly upregulated in patients with severe cirrhosis compared with those who had no cirrhosis (0.012 ± 0.014 vs. 0.0019 ± 0.0026 p = 0.0004)." (PMID 31029128, 2019). "We also concluded that CCN3 was inversely related to cirrhosis in the prognosis of HCC and acted in a negative feedback loop in HSCs." (PMID 31029128, 2019). "However, in the subgroup without cirrhosis, patients with high expression of CCN3 exhibited significantly lower OS (p = 0.016) and higher TRR (p = 0.005) than patients with low expression of CCN3." (PMID 31029128, 2019). "CCN3 was also inversely related to cirrhosis, regulating HSCs through a negative feedback loop." (PMID 31029128, 2019). "In the 186 patients with HCC presented in the previous section, Cox regression analysis revealed a positive correlation between CCN3 expression in non-cancerous hepatic tissues and cirrhosis (p = 0.005), serum ALT (p = 0.023), and vascular invasion (p = 0.013)." (PMID 31029128, 2019). "Thus, high expression of CCN3 may predict poor prognosis in patients with HCC who do not have cirrhosis." (PMID 31029128, 2019).
Cirrhosis (continued). "By contrast, patients with low expression of CCN3 and cirrhosis exhibited a significantly lower OS (p = 0.016) and higher TRR (p = 0.005) than patients without cirrhosis." (PMID 31029128, 2019). "CCN3 was upregulated in non-cancerous hepatic tissues from patients with HCC and cirrhosis (0.0045 ± 0.0040 vs. 0.0022 ± 0.0023 p = 0.0149)." (PMID 31029128, 2019). "In patients without cirrhosis, high CCN3 expression correlated with lower OS and higher TRR compared with those who had low CCN3 expression." (PMID 31029128, 2019).
diabetic kidney disease (2 papers, 2020 to 2023). Progressive kidney disorder caused by vascular damage to the glomerular capillaries, in patients with diabetes mellitus. "A prior study performed same protocol to investigate the role of CCN3 on fibrosis linked to diabetic nephropathy, demonstrating its efficacy in localizing to the heart following interperitoneally injection." (PMID 36998974, 2023). "Also, our previous studies in diabetic kidney disease had shown that dosing CCN3 at 3 times per week was sufficient to block and even reverse fibrosis, so a similar schedule was selected." (PMID 32294968, 2020).
Hypertension (2 papers, 2021 to 2023). The presence of chronic increased pressure in the systemic arterial system. "However, as systemic administration of CCN3 does affect the renal system and potentially other organ systems and various cell types, we cannot rule out off target effects such as hypertension that may indirectly impact reduced cardiac function we observed in our experiments." (PMID 36998974, 2023).
idiopathic intracranial hypertension (2 papers, 2020 to 2021). "A significant positive correlation was found between CCN3 levels in matched plasma and CSF of MS patients which was absent in a comparator group of idiopathic intracranial hypertension patients." (PMID 33222687, 2020). "Interestingly, a significant positive correlation has been reported between levels of the related protein CCN3 in matched plasma and CSF of MS patients, which was absent in a comparator group of idiopathic intracranial hypertension patients." (PMID 35185866, 2021).
Lupus (2 papers, 2006 to 2023). "Lupus patients with thrombocytopenia had higher levels of CCN3 (P = 0.020)." (PMID 37749230, 2023).
metastatic melanoma (2 papers, 2017 to 2019). A melanoma that has spread from its primary site to another anatomic site. "A previous study has shown CCN3 overexpression in metastatic melanoma cells compared with primary tumor cells, and overexpression of CCN3 improves adhesion to ECM proteins by regulating integrin expression." (PMID 29088803, 2017).
Osteopenia (2 papers, 2015 to 2019). Osteopenia is a term to define bone density that is not normal but also not as low as osteoporosis. "CCN3 transgenic mice, in which CCN3 expression was driven by a 2.3-kb Col1a1 promoter, showed osteopenia compared with wild-type mice." (PMID 26395334, 2015).
pancreatic cancer (2 papers, 2017 to 2023). "Similarly, in pancreatic cancer cells, the overexpression of CCN3 facilitated cell proliferation and migration by inducing an epithelial–mesenchymal transition." (PMID 37373471, 2023). "CCN3 has been shown to be a positive regulator of EMT in pancreatic cancer." (PMID 29088803, 2017).
placental disease (2 papers, 2020 to 2024). "Thus, maybe via CCN3 regulation within the placenta, the etiology of theses placental diseases could be explained, leading to novel therapeutic strategies to interfere with them." (PMID 33304321, 2020). "Thus, changes in CCN3 levels alter the expression of senescence markers and the FAK-Akt-mTOR pathway in placental disorders with reduced or increased the proliferation and/or differentiation of CTB." (PMID 33304321, 2020).
psychosis (2 papers, 2019 to 2021). "Furthermore, recent research has also begun to explore the potential mechanisms underlying immune dysfunction in postpartum psychosis (e.g., disturbances in the Treg–CCN3 protein–(re)myelination axis)." (PMID 34704078, 2021). "Conceivably, therefore, any CCN3 effects on psychosis risk might be mediated via DDR1." (PMID 31849729, 2019). "In addition to effects on psychosis risk, perturbed expression of CCN2 and/or CCN3 might impact upon mood symptoms and relevant personality traits." (PMID 31849729, 2019).
renal cell carcinoma (2 papers, 2006 to 2017). "For instance, in renal cell carcinoma, CCN3 promotes cell migration and invasion by upregulating ICAM-1 and COX-2 expression." (PMID 29088803, 2017). "B. Cadot, a new master student in my laboratory got involved in two collaborative studies in which we examined the potential usefulness of CCN3 detection in human prostate tumors and renal cell carcinoma (RCC) for prognosis, typing and therapy." (PMID 16504021, 2006).
small vessel stroke (2 papers, 2024 to 2025). "Higher plasma levels of NovH (encoded by CCN3), an ECM associated protein involved in cardiovascular development, were associated with increased risk of small vessel stroke at pFDR<0.05." (PMID 39011113, 2024).
Alzheimer disease (1 paper, 2006). A progressive, neurodegenerative disease characterized by loss of function and death of nerve cells in several areas of the brain leading to loss of cognitive function such as memory and language. "Considering that brain is a major site of expression for CCN3 and that calmyrin was detected in difuse and senile plaques, the physical interaction of CCN3 and calmyrin and resulting effects on calcium signaling, might also be of significance in the pathogenesis of Alzheimer's disease." (PMID 16895594, 2006).
aneurysm (1 paper, 2021). Bulging or ballooning in an area of an artery secondary to arterial wall weakening. "Indeed CCN3 has been shown to protect against aneurysms, with overexpression viruses lessening the severity of disease, while knockout of CCN3 increased aneurysm severity." (PMID 34080128, 2021).
aortic regurgitation (1 paper, 2023). "Our data suggests that the Mye-CCN3-KO mice develop aortic valve stenosis accompanied with low incidence of aortic regurgitation." (PMID 36670446, 2023).
aortic stenosis (1 paper, 2023). Aortic valve stenosis is a aortic valve disease caused by the incomplete opening of the aortic valve. "Based on Spectral Doppler analysis, peak velocity, peak gradient, and VTI were all significantly elevated in Mye-CCN3-KO mice irrespective of the sex, indicating that myeloid CCN3 deficiency leads to a hemodynamically significant aortic stenosis." (PMID 36670446, 2023).
aortic valve calcification (1 paper, 2023). "To summarize, our data uncovered a novel role of myeloid CCN3 in the regulation of aortic valve calcification." (PMID 36670446, 2023). "In the present study, we investigated the role of macrophage-derived CCN3 in the progression of calcific aortic valve disease." (PMID 36670446, 2023). "In light of this, we speculated that CCN3 might participate in the regulation of aortic valve calcification." (PMID 36670446, 2023). "Our data uncovered a novel role of myeloid CCN3 in the regulation of aortic valve calcification." (PMID 36670446, 2023).
arteriosclerosis (1 paper, 2014). A vascular disorder characterized by thickening and hardening of the walls of the arteries. "Overexpression of CCN3 may improve liver and kidney functions which are deregulated during arteriosclerosis." (PMID 24722330, 2014). "However, the role of CCN3 in arteriosclerosis is not understood." (PMID 24722330, 2014).
Arthritis (1 paper, 2006). Inflammation of a joint. "In particular, the physical interaction of CCN3 with the IL33 cytokine combined with previous data indicating that CCN3 expression was regulated by TNFalpha and IL1 cytokines, point to CCN3 as a potent player in a variety of inflammatory responses, including neurodegenerative disease, and arthritis." (PMID 16895594, 2006).
bone cancer (1 paper, 2012). A primary or metastatic malignant neoplasm affecting the bone or articular cartilage. "However, there is growing evidence that CCN3 can influence the progression of primary bone cancers and act as an important pro-metastatic factor in numerous cancers, including metastatic cancers affecting bone." (PMID 22427255, 2012). "Thus, we will focus this review specifically on these aspects of CCN3 biology as they relate to normal bone turnover, the growth of primary bone tumors and cancers that metastasize to bone." (PMID 22427255, 2012).
brain cancer (1 paper, 2014). A primary or metastatic malignant neoplasm affecting the brain. "However, in the context of brain cancer, NOV appears to inhibit disease progression, but in the context of alveolar rhabdmyosarcoma NOV/CCN3 levels are increased and contribute to survival of oppressive behaviors of the cancerous cells promotes motility." (PMID 25120384, 2014).
cerebral palsy (1 paper, 2006). A group of disorders affecting the development of movement and posture, often accompanied by disturbances of sensation, perception, cognition, and behavior. "Upon selective dorsal rhizotomy, a surgical procedure performed to reduce leg muscle stiffness and spasticity in children who have cerebral palsy, CCN3 expression was increased in dorsal funiculus [, Unpublished data]." (PMID 16895594, 2006).
chordoma (1 paper, 2014). Chordomas are rare malignant tumors arising from embryonic remnants of the notochord in axial skeleton. "Through gene expression analysis, we detected expression of CCN1, CCN2, CCN3 and CCN5 in U-CH1 cells under basal conditions, and demonstrate increased expression of CCN3 and CCN5 by chordoma cells in hypoxia." (PMID 25541962, 2014).
degenerative disc disease (1 paper, 2021). "The trend towards increased TGF-β expression during disc degeneration and reduction in CCN3 expression, accompanied by a simultaneous increase in CCN2 expression, may reflect a reparative response that enhances matrix synthesis and promotes changes in cell numbers." (PMID 33919365, 2021). "Interestingly, some researchers have reported finding that during degenerative disc disease, TGF-β suppresses CCN3 activity and upregulates CCN2 expression, a phenomenon that may be associated with a reparative response." (PMID 33919365, 2021).
demyelinating disease (1 paper, 2020). A broad group of disorders that affect the myelin sheaths that cover the neurons. "As this could have direct relevance for people with demyelinating diseases such as MS, we wanted to determine whether levels of CCN3 should be targeted therapeutically." (PMID 33222687, 2020).
depression (1 paper, 2019). "CCN2 (CTGF) has recently been implicated as a prodepressant molecule on the basis of human and animal model studies, while CCN3 hippocampal expression is decreased ∼1.7-fold in the “chronic social defeat” mouse model of depression." (PMID 31849729, 2019).
dyslipidemia (1 paper, 2014). "Taken as a whole, CCN3 overexpression is associated with control of inflammatory processes and reversion of dyslipidemia." (PMID 24722330, 2014).
gastric cancer (1 paper, 2023). A primary or metastatic malignant neoplasm involving the stomach. "From overall survival analysis, gastric cancer patients with high expression of IGFBP7, CCN2, CCN3, CCN1, CCN5 or CCN4 would have a poor survival time (all p < 0.05)." (PMID 37304887, 2023).
glomerulonephritis (1 paper, 2021). A renal disorder characterized by damage in the glomeruli. "Recently, CCN3 was suggested to play a crucial role in the development of some certain types of glomerulonephritis." (PMID 34393649, 2021). "Furthermore, the proangiogenic and antiangiogenic effects of CCN3 in experimental glomerulonephritis have been determined." (PMID 34393649, 2021). "Therefore, the CCN3 protein can be considered a potential therapeutic target for glomerulonephritis." (PMID 34393649, 2021).
Hepatic steatosis (1 paper, 2025). Steatosis is a term used to denote lipid accumulation within hepatocytes. "The current study provides evidence that elevated expression of CCN3 in the liver of macrophage-specific S100a8-KO mice inhibits CD36 expression and suppresses hepatic steatosis." (PMID 41178716, 2025).
Hypercholesterolemia (1 paper, 2023). An increased concentration of cholesterol in the blood. "To test this hypothesis, we assessed the impact of myeloid CCN3 loss on aortic valve pathology in the context of hypercholesterolemia in conjunction with high fat diet feeding." (PMID 36670446, 2023).
idiopathic pulmonary fibrosis (1 paper, 2025). Idiopathic pulmonary fibrosis (IPF) is a nonneoplastic pulmonary disease that is characterized by the formation of scar tissue within the lungs in the absence of any known cause. "Interestingly, ‘CCL19+ adventitial fibroblasts’ and ‘CCN3+ adventitial fibroblasts’ overexpressed fibroblast activation protein (FAP), a marker of activated fibroblasts and cancer-associated fibroblasts, including in canine idiopathic pulmonary fibrosis and canine lung cancer." (PMID 40114924, 2025).
infarction (1 paper, 2023). A localised pathological necrosis of tissue resulting from obstruction of the blood supply usually by a thrombus, an embolus, or vascular torsion. "We next assessed whether CCN3 administration in mice following infarction resulted in transcriptional changes that promote adverse remodeling." (PMID 36998974, 2023).
leukemia (1 paper, 2019). A malignant (clonal) hematologic disorder, involving hematopoietic stem cells and characterized by the presence of primitive or atypical myeloid or lymphoid cells in the bone marrow and the blood. "Their findings supported the idea that CCN3 can open novel doors for alternate anti-leukemia therapeutics." (PMID 31014357, 2019).
meningioma (1 paper, 2020). A generally slow growing tumor attached to the dura mater. "One of the CCN3 interaction partners is the calcium-binding protein S100-A447, which in our study was identified with a higher abundancy in male meningioma." (PMID 32587372, 2020).
metastatic cancers (1 paper, 2012). A carcinoma which has spread from the original site of growth to another anatomic site. "More recently, emerging evidence suggests that CCN3 may also influence the ability of metastatic cancers to colonize and grow in bone." (PMID 22427255, 2012).
myocardial infarction (1 paper, 2023). Gross necrosis of the myocardium, as a result of interruption of the blood supply to the area, as in coronary thrombosis. "Administration of recombinant CCN3 to adult mice following myocardial infarction remarkably aggravated cardiac function and scarring." (PMID 36998974, 2023). "CCN3 administration drove myocardial gene expression of pro-fibrotic genes in infarcted left ventricles implicating CCN3 as a novel driver of cardiac fibrotic processes following myocardial infarction." (PMID 36998974, 2023). "Yap/Wwtr1 depletion in myofibroblasts attenuates fibrosis and significantly improves cardiac outcomes after myocardial infarction and we identify Ccn3 as a factor downstream of Yap/Wwtr1 that contributes to adverse cardiac remodeling post MI." (PMID 36998974, 2023).
nephropathies (1 paper, 2015). "It has been recently reported that NOV/CCN3 could be involved in kidney damage but its role in the progression of nephropathies is poorly known." (PMID 26367310, 2015).
obstructive sleep apnea (1 paper, 2019). "Emerging data hints that elevated blood CCN3 levels are associated with obstructive sleep apnea (OSA), a common condition associated with impaired sleep and subsequent cognitive processing, and with irritable or depressed mood." (PMID 31849729, 2019).